INS (insulin)
Diseases named in the same sentence as INS in open-access papers (continued):
Sharing a sentence is not in itself a finding about the gene and the disease.
depression (continued). "Chromium has been recognized for enhancing insulin sensitivity in the hypothalamus, promoting the function of serotonin, melatonin, and dopamine, thereby effectively treating neurobehavioral processes like depression and comorbidity." (PMID 38563024, 2024). "Thus, this had mitigated her avoidance to insulin, relieved her state of panic and severe depression." (PMID 39539363, 2024). "Abdominal obesity may affect plasma levels of adiponectin, leptin, cortisol, resistin, insulin, and inflammatory cytokines, such as tumour necrosis factor-α and interleukin-1β, which can enhance neuroinflammation and contribute to depression." (PMID 39487412, 2024). "Disruption of the insulin pathway in the brain is involved in the pathogenesis of depression." (PMID 37649561, 2023). "Moreover, some studies have revealed that the successful treatment of depression can correct insulin response, particularly with more serotonergic agents, such as selective serotonin reuptake inhibitors (SSRIs)." (PMID 36734114, 2023). "In a prior investigation involving adult Dutch diabetic individuals who require regular insulin injections, those struggling with self-injection phobia or self-testing phobia exhibited connections to psychological conditions like depression and emotional disturbances." (PMID 37729191, 2023). "Similarly, significant improvements were observed across time in postprandial insulin levels (22.25 vs. 9.29 μIU/mL), hirsutism (2.98 vs. −0.16 points), and depression (7.73 vs. 1.7 points) (p < 0.05) between the two groups." (PMID 37511908, 2023). "The hypothesis suggests that depression and/or antidepressant use can influence blood glucose levels by inhibiting pancreatic insulin secretion, increasing cellular insulin resistance and/or indirectly affecting insulin secretion with weight gain." (PMID 36766979, 2023). "Several possibilities have been suggested, and there are reports that hypothalamic–pituitary–adrenal axis abnormalities in patients with depression, hypercortisolemia, and immune system abnormalities, including chronic low-grade inflammations, influence the insulin effect." (PMID 36734114, 2023). "In the present study, 85.79% GDM patients (151/176) had received insulin therapy in addition to dietary management, which could have been a factor for stress and depression in these patients." (PMID 37365247, 2023). "We excluded people who were non-fluent in English; morbid obesity (BMI > / = 35 kg/m2); in employment that contraindicates insulin treatment; and those with severe depression, anxiety disorders, psychotic disorders, personality disorders, or cognitive impairment." (PMID 37237318, 2023). "Two patients on a Metformin and insulin combination therapy showed no risk of developing depression." (PMID 37109040, 2023). "Dysregulation of each of these insulin targets could contribute to maladaptive conditions, including eating disorders, as well as in disorders involving depression, anxiety or cognitive or motor dysfunction." (PMID 36979453, 2023). "Additionally, taking medication for a long time and receiving insulin as treatment increased the odds of having depression, as reported in previous studies - similar findings have been reported elsewhere." (PMID 37237354, 2023). "Therefore, management of depression by antidepressant agents improves glucose homeostasis and insulin sensitivity." (PMID 37653558, 2023). "Those who do not take insulin were less likely to score higher (worse) than those who do take insulin on mobility (OR = 0.7, 95% CI: 0.5–0.9, p < 0.01), pain/discomfort (OR = 0.8, 95% CI: 0.6–1.0, p < 0.05), and anxiety/depression (OR = 0.5, 95% CI: 0.4–0.70, p < 0.001) sub-scales." (PMID 37033039, 2023). "Of note, T2D increases incidence of depression by 29%, this percentage may rise to 53% in T2D patients treated by insulin." (PMID 37653558, 2023).
depression (continued). "Of interest, the beneficial and detrimental effects of antidepressants in T2D patients with depression may relate to the severity of depression which affects insulin sensitivity and glucose homeostasis." (PMID 37653558, 2023). "Studies further suggest that insulin-sensitizing agents could play a significant role in the treatment of major depression, particularly in patients with documented IR." (PMID 35365803, 2022). "First, red meat rich in saturated fatty acids may be related to cardiovascular disease by promoting insulin sensitivity, and cardiovascular disease may be involved in the pathogenesis of depression." (PMID 35330707, 2022). "In this study, BCP was able not only to ameliorate fasting blood glucose, insulin resistance and insulin level parameters, but was also able to improve memory and alleviate anxiety and depression in a CB2-dependent manner (proven through AM630 CB2 antagonist administration)." (PMID 35276827, 2022). "In the pathophysiology of anxiety and depression following metabolic disorders in aging, it appears that impaired glucose and insulin metabolism may lead to changes in cortisol." (PMID 36583177, 2022). "In addition, the increased FFA and INS levels in the serum of mice with depression-like behaviors were significantly downregulated after 5-HTP treatment." (PMID 35572711, 2022). "Injecting insulin will affect the depression of diabetic patients." (PMID 35538471, 2022). "Although insulin levels were not measured, a low insulin level is a risk factor for developing depression." (PMID 35401344, 2022). "LA increased insulin sensitivity and reduced the manifestations of depressive disorder." (PMID 35631318, 2022). "As reported, high intakes of starch and sugars can lead to hypoglycaemia because of an acute response to insulin; thus, this could induce central dysfunction and depressive disorder by influencing hormone levels." (PMID 35745131, 2022). "Depression-like behaviors were associated with age, body image-related factors (including BMI and WHR), hyperandrogenism-related factors (including FAI and hirsutism), and metabolic factors (including fasting insulin, FBG, and HOMA-IR)." (PMID 34744814, 2021). "Secondary outcomes included type of delivery, prematurity, small- for-gestational-age (SGA) or large-for-gestational-age (LGA) infants, macrosomia, Apgar score, insulin use, depression, respiratory quotient (RQ), resting metabolic rate (RMR) and middle-upper arm circumference (MUAC)." (PMID 34371966, 2021). "Literature related to depression and insulin is collected into a specific database." (PMID 34366917, 2021). "Propionate exhibited a positive correlation with insulin concentrations and with the relative depletion of the propionate producer Roseburia inulinivorans, whereas butyrate levels were negatively correlated with anxiety and depression." (PMID 33652962, 2021). "Major depressive disorder (MDD) is positively correlated with impaired insulin action/IR." (PMID 34209599, 2021). "Thus, the current study as well as these future studies would provide more evidence to support PL/CS hormone levels as a potential marker of peripartum depression and insulin treatment as a possible preventative measure." (PMID 33743677, 2021). "Hence, insulin resistance can be a possible cause of depression in women with PCOS, and alternatively, treating abnormal insulin levels can reduce the development of depression." (PMID 33777576, 2021). "Publications have proved the connection between insulin and depression." (PMID 34366917, 2021). "Insulin and exercise have a share mechanism to relieve depression." (PMID 34366917, 2021). "In addition, the profiles are characterized by variables relating to perceived financial insecurity, taking insulin treatment, having depression, and the care received’s congruence with that of the CCM." (PMID 33481883, 2021).
depression (continued). "In addition, several precipitating factors for DKA were identified including infections, skipping insulin therapy, mode of insulin delivery, myocardial infarctions, stroke, depression, trauma, and substance abuse." (PMID 33668749, 2021). "In the PE program, we found a positive correlation between insulin and depression symptoms." (PMID 33681273, 2021). "Therefore, study aims to comprehensively analyze current status and development trend on the link between insulin and depression from 2010 to 2020 through bibliometrics." (PMID 34366917, 2021). "ALA increases insulin sensitivity, which could increase serotonin synthesis and thus reduce the manifestations of depressive disorder." (PMID 33614362, 2021). "A cohort study that followed 65,381 women for 10 years found that the risk of developing clinical depression was higher in diabetic women, particularly in those who received insulin therapy, compared with non-diabetic women." (PMID 32270255, 2020). "The regulation of insulin on depression and depression‐like behaviour has been widely reported." (PMID 32281722, 2020). "These associations persisted after adjustment for other patient characteristics and were driven by significantly poorer scores in each domain of the EQ‐5D questionnaire, with the exception of anxiety/depression in which solely insulin‐treated DM patients fared worse." (PMID 33146924, 2020). "This study therefore aimed to investigate the impact of psychological aspects (i.e.illness perceptions, coping strategies, insulin beliefs, depression, and anxiety),age, and BMI, on ED psychopathology among adults with T1D, with a particular focuson gender differences." (PMID 33282331, 2020). "Unraveling the relationships between depression and impaired insulin signaling could be a matter of great importance as we pursue an understanding of the associated pathophysiology and explore alternative treatment options." (PMID 32971941, 2020). "Evidence from investigations of the antidepressant properties of repurposed anti-hyperglycemic agents may provide new insight into the role of brain insulin signaling in the pathophysiology of depression." (PMID 32971941, 2020). "Intranasally administered insulin could attenuate the hypothalamic–pituitary–adrenal (HPA) axis response to psychosocial stress, which has been associated with depression in numerous previous studies." (PMID 32971941, 2020). "Thus, AN appears as a condition characterized by endocrinologic stress and adaptation to starvation with increased insulin sensitivity, coexisting with psychologic stress, anxiety, and depression." (PMID 32073757, 2020). "This might be due to injection for insulin may cause discomfort, and these group diabetic patients (both oral antidiabetic medication and insulin) are more likely to have poor glycemic control this might eventually lead to develop depression symptoms." (PMID 33145110, 2020). "Therefore, the objective of this review was to delineate the antidepressant effects of insulin and anti-hyperglycemic agents in human subjects with depression." (PMID 32971941, 2020). "The mechanism by which insulin improves memory and alleviates depression may be that insulin regulates synaptic plasticity in the hippocampus." (PMID 32281722, 2020). "The insulin signaling system has been proposed as a novel target in the treatment of depression." (PMID 32971941, 2020). "In young depression patients, insulin sensitivity is significantly decreased." (PMID 32281722, 2020). "The exposure of adult nocturnal rodents to LL disrupts the circadian rhythms of locomotor activity, body temperature, and plasma melatonin level; attenuates circadian rhythms in the cardiovascular system; alters insulin secretion; compromises the immune system; and leads to anxiety and depression." (PMID 33297440, 2020). "The probability of depression was 9.11 times higher among who used insulin (p<0.001)." (PMID 31181109, 2019).
depression (continued). "However, multivariate analysis showed that the only significant factors for depression were older age, education below secondary level, homemaker, smaller family size, using insulin and having an additional illness." (PMID 31181109, 2019). "Another significant association in this study was seen with insulin use which showed higher chances of depression (OR = 9.11) compared to those not using insulin." (PMID 31181109, 2019). "Metabolism, cognition, and mood are strictly intertwined; if glucose toxicity can directly interfere with the cognitive functions, the insulin pathway is involved in amyloid formation, while depression can precipitate neuronal damage through inflammatory mechanisms." (PMID 31178961, 2019). "Also, the results showed that an individual receiving insulin injection experience a slight but significant depression (mean = 44.19, SD = 10.63) than individuals using oral drugs management (mean = 42.85, SD = 12.05, t = 1.158, p < 0.05)." (PMID 31890668, 2019). "Exclusion of co-exposed infants from the analysis reduced confounding by co-exposure: use of insulin, AEDs, coumarins, substances and alcohol was higher amongst women with depression, medicated and unmedicated, and adverse perinatal outcomes were more prevalent following these exposures." (PMID 31738813, 2019). "However, because all three of these studies did not have a control group, it is possible that factors other than the depression interventions were responsible for the observed improvements in insulin sensitivity." (PMID 30138433, 2018). "Moreover, AICAR treatment can improve depression-like behaviors as efficiently as treadmill running in a mouse model of depression-like and insulin-resistant state." (PMID 29021780, 2017). "O3-FAs may be beneficial for predicting survival outcomes in coronary heart disease, insulin sensitivity, for improving bone health, for treatment of depression, and for improving cognition and memory." (PMID 28837086, 2017). "The hypothalamic serotonin is increased during insulin-induced hypoglycemia, indicating that glycemic homeostasis may be beneficial for ameliorating depression." (PMID 27553852, 2016). "Prior studies suggested that short-term anti-depressive treatment of nondiabetic depressed patients has a beneficial effect and improve insulin sensitivity together with improving depression, but on the long run, the effects might be opposite." (PMID 27453739, 2016). "Indeed, metabolomics has been used previously as such an approach in studies of cardiovascular disease, insulin sensitivity, depression and cancer." (PMID 26626856, 2015). "Increased insulin sensitivity, which has been noted in patients who have remitted depression using SSRI’s, could also serve to positively affect serum glucose levels." (PMID 26231223, 2015). "Blood glucose, insulin, blood pressure, arterial stiffness, physical activity, eating behaviour, mental well-being (stress, anxiety, and depression), social support, self-control, self-efficacy, Facebook activity, and program evaluation are secondary outcome measures." (PMID 26012783, 2015). "However, use of insulin and sulfonylureas is associated with weight gain, and if one views weight gain and possibly overweight and obesity as a type of unspecific stress, the pathophysiological mechanisms addressing how stress can cause depression might also be relevant in this context." (PMID 26457080, 2015). "Secondary outcome measures will be blood glucose, insulin, blood pressure, arterial stiffness, physical activity, eating behaviour, mental well-being (stress, anxiety, and depression), social support, self-control, self-efficacy, Facebook activity, and program evaluation." (PMID 26012783, 2015). "The pathophysiology of this link could be due to hypothalamic pituitary adrenal axis hyperactivity (HPA) and mental stress induced symphathomedullary activation in patients with major depression leading to decreased glucose transport and insulin resistance." (PMID 26552427, 2015).
depression (continued). "Potential pathophysiological mechanisms include effects of stress and depression acting via cortisol to stimulate glucose production, increase lipolysis and circulating free fatty acids, decrease insulin secretion, and decrease sensitivity to insulin." (PMID 24507417, 2014). "The possible explanations for the differences are that those on insulin regimen might be more likely to feel better and to have less symptoms of dizziness, depression, fatigue, thirst and dry mouth, polyuria, and nocturia than their non-insulin counterparts." (PMID 25895200, 2014). "Factors associated both with MCI and depressive syndrome were as follows: female gender, single marital status, past smoking status, retinopathy, presence of previous CVD or stroke, increased number of comorbidities, and insulin treatment." (PMID 25431771, 2014). "Consultation practices may also play a role in the relation between depression and insulin initiation." (PMID 24223860, 2013). "However, in the original four publications we did not see any clear benefits on the main endpoints body weight, insulin sensitivity as evaluated by a hyperglycemic clamp, bone density, or symptoms of depression." (PMID 23577264, 2013). "If depression systematically leads to an earlier start of insulin therapy in some people but to later insulin commencement in others, these opposite effects may cancel each other out when averaged at the group level." (PMID 24223860, 2013). "Given its close relation with suboptimal glycemic control, depression may also be related to an earlier start of insulin therapy." (PMID 24223860, 2013). "Ultimately, the decision to initiate or refrain from insulin therapy stems from a combination of individual patient and provider factors and characteristics of the health care system, and depression may feed into these processes in a myriad number of ways." (PMID 24223860, 2013). "However, preliminary results from a small Dutch primary care study (n = 152) suggest that people who switch over to insulin therapy due to secondary failure more frequently suffer from depression." (PMID 24223860, 2013). "Additionally, South Asians had more prominent abnormalities in fibrinogen, plasminogen activator inhibitor 1, homocysteine, C-reactive protein, insulin sensitivity, and psychosocial factors (stress, depression)." (PMID 24163770, 2013). "Patients with depression also have some cognitive function problems and maybe have differential expression of genes involving in insulin signaling pathway." (PMID 22348066, 2012). "The authors, evaluating 258 T2DM patients, observed that depression was associated with A1C levels in patients using insulin (beta = 0.35; p < 0.001) but not in patients using oral agents alone (beta = -0.08; p = NS)." (PMID 21978660, 2011). "The insulin-treated patients demonstrated a tendency towards higher depression scores (p < .10)." (PMID 20920319, 2010). "Circulating interleukin and other cytokines also affect insulin function, together suggesting that a complex interplay of disrupted hormone-mediated regulations of organs and cell ensembles may occur in depression." (PMID 20376317, 2010). "Thus the effects of antidepressants on insulin sensitivity and proinflammatory responses will be a crucial issue for depression treatment." (PMID 20490354, 2010). "Here again, we must make note of the connection between oxidative stress, insulin and depression." (PMID 21143923, 2010). "Additionally, depression was significantly associated with insulin use, even among patients with good GC, regardless of HbA1c levels." (PMID 40429455, 2025). "Notably, higher C-peptide levels were associated with better mobility and fewer symptoms of anxiety and depression, suggesting that residual endogenous insulin production may support both physical function and mental well-being." (PMID 41153704, 2025).